NLRC4 (NLR family CARD domain containing 4)
Diseases named in the same sentence as NLRC4 in open-access papers (continued):
Sharing a sentence is not in itself a finding about the gene and the disease.
infection (continued). "In an earlier report, we showed that PAO1 infection of peritoneal neutrophils induced release of IL-1β that was attenuated (~50-60%) but not completely suppressed in neutrophils from caspase-1-/- and Nlrc4-/- mice." (PMID 37730693, 2023). "While IL-1β release from ΔexoST infected neutrophils is also NLRC4-dependent, infection with PAO1 is instead NLRP3-dependent and driven by the ADP ribosyl transferase activity of ExoS." (PMID 37730693, 2023). "We therefore challenged B6.Nlrc4–/–Casp11+/– and B6.Nlrc4–/–Casp11–/– littermates with WT Shigella and assessed pathogenicity for 2 days following infection." (PMID 36645406, 2023). "We conducted a similar time-course infection study in normal and NLRC4−/− mice to assess the role of NLRC4 inflammasome in combating P. aeruginosa infection." (PMID 35277504, 2022). "NLRP3 and NLRC4 are two of the key inflammasomes that are of importance during infection with Salmonella." (PMID 34864057, 2022). "Given the central role of NAIP/NLRC4 inflammasomes in controlling infection and, also, induction of inflammatory pathologies, many efforts have been made to uncover novel molecules involved in their regulation." (PMID 36481780, 2022). "NLRC4 Ser533Ala knock-in mice were generated by two groups independently and used in S. Tryphimurium in vivo infection models and in ex vivo mechanistic studies using bone marrow derived macrophages (BMDMs)." (PMID 35800898, 2022). "Caspase-1 activation was significantly increased in Nlrc4−/− BMDMs during infection with ΔfliCΔgalE and ΔfliCΔgalE::pBAD33 strains compared to ΔfliC, but no such differences were observed in Nlrp3−/− BMDMs infected with different mutant strains." (PMID 35630356, 2022). "Regardless of strain genetic background, wounds in Cas-1–/–, ASC–/–, and Nlrc4–/– mice were significantly more vulnerable to infection with P. aeruginosa as they contained >1 log-order more bacteria than wounds in C57BL/6 normal mice." (PMID 35277504, 2022). "Conversely, NAIP/NLRC4 in phagocytes is dispensable for the restriction of Salmonella dissemination and replication at infection sites during early infection." (PMID 35888979, 2022). "Despite that C. violaceum has evolved to inhibit the apoptosis and NF-κB pathways, its infection features extensive lytic death through NLRC4 inflammasome-mediated pyroptosis as well as the action of secreted hemolytic toxins." (PMID 35446120, 2022). "P. aeruginosa strain PAO1 infection is able to activate NLRC4 and NLRP3 inflammasomes and initiate a type of rapid inflammatory cell death termed pyroptosis in macrophages." (PMID 36604139, 2022). "This means that the ability of mouse epithelial cells to detect infection via the NAIP/NLRC4 inflammasome pathway is crucial to prevent bacterial virulence." (PMID 35801644, 2022). "In contrast, infection of WT and Nlrc4-/- BMNs with P. aeruginosa strains of which neutrophil cell lysis is partially Caspase-1-dependent (PAO1 and CHA strains) also showed a partial involvement of NLRC4 in controlling neutrophil lysis." (PMID 35849616, 2022). "The transcripts of Tlr1, Tlr5, Tlr11, and Nod2, Nlrp1a, Naip2, and Nlrc4 were significantly higher in the Nlrp3−/− than wild-type mice on day 7 post-infection." (PMID 34690967, 2021). "T. gondii infection time-dependently induced NLRP3 and ASC protein expression, adequately induced NLRP6 and cleaved caspase-1 expression, and moderately induced NLRC4 expression at 4 h post-infection." (PMID 33712075, 2021). "We detected significantly more S.Tm-G+ infection foci, and higher total S.Tm CFUs in 3D enteroids derived from Nlrc4−/− mice than in WT control enteroids at ~4 h p.i. onwards." (PMID 33731826, 2021). "Salmonella typhimurium (S. typhimurium) infection of macrophage induces NLRC4 inflammasome-mediated production of the pro-inflammatory cytokines IL-1β." (PMID 33664876, 2021).
infection (continued). "To address this, we first extended the in vivo infection kinetics experiments to 18 h p.i and focused on dislodging enterocytes in Nlrc4−/− mice." (PMID 33731826, 2021). "Our data confirm that both NLRP3 and NAIP/NLRC4 contribute to the inflammasome response in human macrophages upon infection with S. Typhimurium, but the relative contribution of various ligands of this bacterium is unclear." (PMID 33380493, 2021). "Intriguingly, a recent paper reported that NLRC4 inflammasome activation is independent on phosphorylation during infection." (PMID 33664876, 2021). "Briefly, in a murine model of infection, Burkholderia is initially detected by macrophages through the Naip/Nlrc4 inflammasome, and the consequent IL-18 release triggers the production of IFN-γ whereby in neutrophils and macrophages, caspase-11 is upregulated." (PMID 34399626, 2021). "Together, these data suggest that both NLRP3 and NLRC4 contribute to the inflammasome response to infection with S. Typhimurium of human macrophages." (PMID 33380493, 2021). "In conclusion, PA infection attenuated macrophage phagocytosis through activation of NLRC4 inflammasome in macrophages, which eventually led to pulmonary inflammatory damage in mice." (PMID 33489931, 2020). "In sharp contrast, our analysis proves phagocyte NAIP/NLRC4 to be dispensable for restriction of S. Tm migration to, and replication at, systemic sites during early infection." (PMID 31953493, 2020). "In a subsequent infection, 80% (8/10) of 129.Nlrc4–/– mice had bloody stool (occult blood only, n = 5; macroscopically visible blood, n = 3)." (PMID 33074100, 2020). "It has been demonstrated that severe infection injury can promote the activation of NLRC4 as well as NLRP3 inflammasome, regulate the activation of Caspase-1, and eventually lead to inflammatory injury." (PMID 33489931, 2020). "As expected, the levels of NLRP3 and NLRC4 were significantly increased after infection with S. Typhimurium." (PMID 33384666, 2020). "NLRC4 inflammasome in macrophages can be activated and subsequently induce downstream inflammatory response upon sensing presence of PA infection." (PMID 33489931, 2020). "We thus crossed Nlrc4−/− mice with Nlrp3- or Casp11-knockout animals to obtain Nlrc4−/−Nlrp3+/− and Nlrc4−/−Nlrp3−/− littermates, as well as Nlrc4−/−Casp11+/− and Nlrc4−/−Casp11−/− littermates, for infections." (PMID 31953493, 2020). "By conventional plating, we detected ~10-fold increased total S. Tm loads in the mLN of Nlrc4−/−64 mice compared to their heterozygous littermate controls at 24 h post-infection (hpi) (“all S. Tm”)." (PMID 31953493, 2020). "It should here be noted that luminal S.Tm loads in wild-type and Nlrc4-deleted mice are equal during early infection." (PMID 32365138, 2020). "Collectively, these results indicate that the production of IL-18, while mediated by NLRP6 in the initial phase of infection, is then dependent on NLRC4, more than NLRP3." (PMID 31681274, 2019). "As IL-22 promotes NLRC4 activity in infection, this highlights the cross-talk between IL-22 and IL-18 in VVC." (PMID 31681274, 2019). "To confirm association of NLRP3, NLRC4 and NAIP with ASC during CFT073 infection of THP-1m, we performed immunoprecipitation of ASC and detected NLRP3, NLRC4 and NAIP proteins." (PMID 31551961, 2019). "by PRRs remains mostly unidentified, it was seen that infection by A phagocytophilum, the etiologic agent of human granulocytic anaplasmosis, induces activation of the NLRC4 inflammasome." (PMID 31134081, 2019). "Studies have shown that many proteins of Salmonella can activate intracellular NLRC4 (NLR family, CARD domain containing-4) inflammasome response, but Salmonella can escape the inflammasome response during the process of infection." (PMID 29523140, 2018). "Salmonella induces YAP phosphorylation during B cell infection, triggering the transcriptional downregulation of the Nlrc4 gene." (PMID 30103648, 2018).
infection (continued). "Conversely, in Il9R−/− mice, the IL-22/NLRC4 axis was not only maximally induced but also maintained throughout the infection." (PMID 30515173, 2018). "When we deleted sopB in Salmonella, infected B cells that lack Rictor, or inhibited the signaling cascade using a pharmacological approach, we were able to restore the function of the NLRC4 inflammasome in B cells and the ability to control the infection." (PMID 30103648, 2018). "Since NLRC4 levels were significantly elevated compared with those of NLRP3 after infection, we focused on NLRC4." (PMID 28961278, 2017). "Using flagellin-positive bacteria such as L. pneumophila, L. gratiana and L. micdadei, we demonstrated that Asc/Casp1/11-/- mice were highly permissive to bacterial replication and phenocopied infection of Nlrc4-/- mice." (PMID 28771586, 2017). "Upon infection of mammalian macrophages, cytosolic flagellin triggers the activation of Naip/NLRC4 inflammasome, which culminates in pyroptosis and restriction of bacterial replication." (PMID 28771586, 2017). "In our study, expression of TLR4, TLR5, NLRC4, caspase-4, and matured IL-18 and IL-1β cytokines was induced in hCFs after infection with P. aeruginosa wild-type strains." (PMID 28469996, 2017). "EscI protein, the inner rod protein of enteropathogenic E. coli, is secreted in the early stage of infection and its C-terminal sequence can activate the NLRC4 inflammasome." (PMID 28468643, 2017). "This can occur through the T3SS1 protein PrgJ that can activate the NLRC4 inflammasome in macrophages, but is only expressed during the early stage of infection." (PMID 28468643, 2017). "The selectivity of the fenamates to NLRP3 over other inflammasomes reported here is another advantage since their use would avoid compromising NLRC4 or AIM2 inflammasome-dependent host responses to infection." (PMID 27509875, 2016). "The opposing findings observed with flagellin, further suggest the protective role of the TLR5/NLRC4 axis in infection." (PMID 26972847, 2016). "Infection with Salmonella enterica serovar Typhimurium (S. Typhimurium) triggers the formation of a complex inflammasome that can include NLRC4, NLR family PYRIN domain-containing protein 3 (NLRP3), ASC, caspase-1 and caspase-8 (refs 5, 17, 18, 19)." (PMID 27670879, 2016). "To unravel the functional activity of either NLRP3 or NLRC4 in these infection models, we assessed Nlrp3–/– or Nlrc4–/– mice for susceptibility to either infection and inflammasome activity." (PMID 26972847, 2016). "In contrast, Nlrc4 -/- BMDMs had a similar number of inflammasome foci upon infection as wildtype macrophages." (PMID 27011353, 2016). "Caspase-1-dependent activation of caspase-7 in murine C57BL/6 macrophages upon infection with L. pneumophila requires detection of bacterial flagellin by the host proteins Naip5 and Nlrc4." (PMID 27148204, 2016). "The NAIP5/NLRC4 inflammasome is perhaps the best-studied inflammasome complex with regard to resistance to infections." (PMID 25071770, 2014). "NAIP/NLRC4 are most likely the best-studied inflammasomes in the context of host resistance against infections." (PMID 25071770, 2014). "Taken together we identified an activation pathway involving caspases-1, -9, -7 and PARP downstream of the host receptor NLRC4 in the early phase of infection with B. pseudomallei E8." (PMID 24626296, 2014). "Although the involvement of NLRC4 in the control of infections was previously reported, their agonists remained a mystery until 2006." (PMID 25071770, 2014). "In one previous study, infection by S. typhimurium resulted in NLRC4- and caspase-1-dependent secretion of IL-1α." (PMID 25071770, 2014). "NLRC4 plays a central role in host defense following infection with several pathogens, such as Legionella pneumophila, Candida albicans, S. typhimurium, Burkholderia pseudomallei, and Pseudomonas aeruginosa." (PMID 25071778, 2014).
infection (continued). "Forty eight hours after infection, bacterial growth in the lungs of both Nlrc4−/− and Casp1−/−Casp11−/− mice had increased significantly compared to wild type mice (by 1.87 log10 CFU and 2.69 log10 CFU, respectively)." (PMID 25232720, 2014). "Collectively, our data indicate that L. pneumophila triggers caspase-11 activation and IL-1α release independently of the ASC and NLRC4 inflammasomes during both in vitro and in vivo infection." (PMID 23762026, 2013). "We next examined lung histology in WT, Nlrc4−/−, and Nlrc4−/−/Tlr5−/− mice at 1 and 3 days after infection and determined the percentage of inflamed airspace." (PMID 23937571, 2013). "Caspase-1 activation and the processing/release of IL-1β were completely inhibited in the infection of NLRP3- and ASC-deficient BMMs, whereas inhibition was marginal in NLRC4-deficient cells." (PMID 23357873, 2013). "At higher MOIs, infection of B6 macrophages induces both NLRC4-dependent and NLRC4-independent inflammasome activation." (PMID 24409420, 2013). "Infection with the ΔtdhASΔh1 mutant confirmed that NLRP3/NLRC4-inflammasomes activation is triggered by T3SS1." (PMID 23357873, 2013). "In the absence of priming, minimal levels of IL-1β were secreted by WT, Nlrp3−/− and Nlrc4−/− macrophages during infection with WT and Δhly L. monocytogenes." (PMID 24058709, 2013). "To identify the effector genes, we further introduced a deletion in the h2, h3 or h4 region and examined NLRC4 inflammasome activation after infection with the h2, h3, or h4 mutants as well as the h1 mutant in NLRP3-deficient BMMs." (PMID 23357873, 2013). "The NLR family member proteins NLRP3 and NLRC4 are known to recognize infection with various pathogens and to mediate caspase-1 activation by forming a complex with adaptor protein ASC." (PMID 23357873, 2013). "Supporting NLRC4 influenced bacterial clearance, Salmonella enterica promotes its own survival and prevents the clearance of infection by down regulating NLRC4 in B-cells." (PMID 24312669, 2013). "NLRC4 plays an essential role in host survival and pathogen clearance following host infection with pathogens such as Legionella pneumophila, Candida albicans, and Burkholderia pseudomallei." (PMID 24137163, 2013). "The Nlrc4 inflammasome also controls intraperitoneal infection of mice from Salmonella that overexpress flagellin, where Nlrc4–mediated protection is dependent on pyroptosis and independent of IL-1B and IL-18." (PMID 23977202, 2013). "The immune response of Nlrc4−/−, Nlrc4−/−/Tlr5−/−, and wild type C57Bl/6 mice was analyzed after in vivo infection with aerosolized Lp." (PMID 23937571, 2013). "Our primary finding is that TLR5 and NLRC4 mediate different roles in the inflammatory response to Lp flagellin in an aerosolized infection model." (PMID 23937571, 2013). "Nlrc4−/−/Tlr5−/− mice also had altered cytokine production at both 4 and 24 hours post infection when compared to wild-type (WT) and Nlrc4−/− mice." (PMID 23937571, 2013). "We analyzed the proteins that co-precipitated with NLRC4 after infection with the ΔtdhASΔvopQ mutant or the ΔtdhASΔvopS mutant." (PMID 23357873, 2013). "At 4 h post-infection, the lungs of Nlrc4−/−/Tlr5−/− had decreased levels of tumor necrosis factor (TNF) compared to WT control lungs." (PMID 23937571, 2013). "In these cells, the NLRC4 inflammasome is activated upon infection with Salmonella, whereas the activation of NLRP3 inflammasome is not triggered by the NLRP3 stimulators such as ATP." (PMID 23357873, 2013). "During the systemic phase of infection, S. Typhimurium is able to completely suppress flagellin expression, which results in evasion of NLRC4 detection and subsequent pyroptosis." (PMID 23055923, 2012). "A previous report showed that in response to infection with Salmonella typhimurium at early time points IL-1β secretion and cell death are NLRC4 dependent." (PMID 22216309, 2011).
infection (continued). "This is in contrast to the components required to respond to PA103 infection, which is dependent on NLRC4 and ASC as well as caspase-1." (PMID 20955240, 2011). "Yet in our in vivo model on mucosal candidiasis, NLRC4 is required for protection from mucosal colonization, prevention of early dissemination of infection, and neutrophil infiltration." (PMID 22174673, 2011). "Previous studies have demonstrated that NLRP3 expression is inducible following infection and implicate this as the rate limiting step in inflammasome activation but little is known about the regulation of NLRC4 expression." (PMID 22174673, 2011). "During the early phase of the infection the NLRC4 inflammasome also significantly contributes to IL-1β production." (PMID 22241982, 2011). "This is likely due to the fact that WT cells rapidly die after infection while Nlrc4-/- cells remain viable and continue to synthesize and secrete IL-1β." (PMID 22241982, 2011). "We show that infection with Candida albicans leads to up-regulation of NLRP3 and NLRC4 expression in the oral mucosa and this induction is impaired in both NLRP3 and NLRC4 deficient mice." (PMID 22174673, 2011). "Production of IL-1β during the first hours of the infection was also significantly reduced in Nlrc4-/- cells." (PMID 22241982, 2011). "Taken together these results show that infection of macrophages and dendritic cells with B. pseudomallei leads to activation of the NLRC4 and NLRP3 inflammasomes." (PMID 22241982, 2011). "NLRC4 contributes to IL-1β during the early phase of the infection and induction of pyroptosis that restricts bacterial growth." (PMID 22241982, 2011). "Previous reports have demonstrated activation of both NLRP3 and NLRC4 inflammasomes in response to infection with Legionella pneumophila, Listeria monocytogenes, and Salmonella typhimurium." (PMID 22241982, 2011). "NLRC4/IPAF responds to the presence of flagellin within the macrophage cytosol during infection by Salmonella, Legionella and Pseudomonas." (PMID 22315529, 2010). "Accordingly, mouse macrophages that do not activate caspase-1 in response to L. pneumophila such as Nlrc4−/− and caspase-1−/− cells are permissive to infection." (PMID 19343209, 2009). "Using the intracellular pathogen L. pneumophila, we show that, upon infection of murine macrophages, caspase-7 was activated downstream of the Nlrc4 inflammasome and required caspase-1 activation." (PMID 19343209, 2009). "In the absence of this defence, i.e., in NLRC4-deficient mice, the tissue loads are exacerbated, leading to the loss of gut epithelial integrity within 72 h following infection with wild-type S. Tm (S. TmWT)." (PMID 41370284, 2025). "Under AJ01 infection, NLRC4 is internalized from the cell membrane into the cytoplasm." (PMID 40085533, 2025). "Future studies using oral infection models are necessary to determine whether NLRC4-dependent mechanisms similarly operate in mucosal environments." (PMID 41304196, 2025). "Until now, the primary role attributed to the NAIP/NLRC4 inflammasome has been its activation in triggering the inflammatory response of the host, thereby contributing to defense against infection by limiting bacterial proliferation within infected cells, predominantly macrophages." (PMID 40158217, 2025). "The NLRC4 inflammasome, vital for immune defense, responds to infections and inflammation." (PMID 38177670, 2024). "Another lncRNA, LNCGM1082, induced by S. typhimurium in macrophages serves as a molecular scaffold, mediating the binding of protein kinase Cδ with the inflammasome NLRC4 to induce the phosphorylation and activation of NLRC4, thereby promoting the host immune defense against infection." (PMID 38542512, 2024). "As a consequence, we interrogated if mAdV3 is generally able to modify host inflammasome responses by individually activating NLRP3 (by nigericin treatment), AIM2 (by poly-dAdT transfection) and PYRIN (by treatment with UCN-01) and NLRC4 (infection with SPI-1 induced Salmonella)." (PMID 39366977, 2024).